ERBB2 (erb-b2 receptor tyrosine kinase 2)
Diseases named in the same sentence as ERBB2 in open-access papers (continued):
Sharing a sentence is not in itself a finding about the gene and the disease.
breast cancer (continued). "In response to the mitochondrial dysfunction previously shown to be induced by buformin, we observed concomitant upregulation of p-AMPK and downregulation of p-mTOR and downstream targets, p-p70S6K and p-4EBP1, in erbB-2-overexpressing breast cancer cells in vitro." (PMID 28193239, 2017). "Thus, Mek-induced ErbB2 stabilization in detached breast cancer cells is critical for their ability to grow anchorage-independently and their trastuzumab sensitivity." (PMID 29285258, 2017). "However, in contrast to breast cancer, the treatment of ErbB2 overexpressing tumours of the endometrium and stomach did not yield comparable positive results." (PMID 28417948, 2017). "The isoform switch that occurs after p110α loss raises the concern about using isoform-specific inhibitors as a way to reach durable remission in patients who have ErbB2-positive breast cancer, and allows us to suggest a therapeutic approach that is potentially more effective." (PMID 28783168, 2017). "To identify genes whose suppression converts the cytostatic response to PI3K inhibition into a cytotoxic response, we performed a positive-selection genome scale shRNA screen using MDA-MB-453 breast cancer cells, which harbor a PIK3CA H1047R mutation and ERBB2 amplification." (PMID 28561737, 2017). "Based on our genetic studies, we could predict that treatment of ErbB2-positive breast cancer with a p110α-specific inhibitor would lead to the development of resistance through dependency on p110β." (PMID 28783168, 2017). "We also tested whether ERRF functionally modulates the responses of ERBB2-positive breast cancer cells to the lapatinib ERBB2 inhibitor." (PMID 28415602, 2017). "The ERBB2, GRB7 and MIEN1 genes, which are located on chromosome 17 in relative proximity within a region including approximately 60,000 base pairs, have been reported co-amplified and associated with poor prognosis in breast cancer." (PMID 28832682, 2017). "In an effort to further understand the mechanisms that control ErbB2-dependent three-dimensional growth of breast cancer cells we found in this study that Mek activity is required for the expression of ErbB2 itself in ErbB2-positive breast cancer cells detached from the ECM." (PMID 29285258, 2017). "Also, we found significantly greater peptide binding to pre-clinical xenograft breast cancer in vivo and to human specimens of invasive ductal carcinoma that express ErbB2 ex vivo." (PMID 29089571, 2017). "We further tested whether Mek inhibition promotes covalent binding of ErbB2 to a protein ubiquitin and subsequent ErbB2 proteasomal degradation (a known mechanism of protein turnover) in detached breast cancer cells." (PMID 29285258, 2017). "Phenformin also blocked epithelial-mesenchymal transition, decreased the invasive phenotype, and suppressed receptor tyrosine kinase signaling, including insulin receptor substrate 1 and IGF1R, in ErbB2-overexpressing breast cancer cells and mouse mammary tumor-derived tissues." (PMID 28947975, 2017). "An ErbB2 amplification occurs in about 15–20% of breast cancers." (PMID 28417948, 2017). "erbB-2/Her2+ breast cancers account for approximately 30% of breast cancer cases." (PMID 28061785, 2017). "Therefore, we aimed to investigate the effects of buformin on erbB-2-overexpressing breast cancer with in vitro and in vivo models." (PMID 28193239, 2017). "Although novel ErbB2‐targeted agents have been developed since trastuzumab was first approved, resistance to these ErbB2‐targeted therapies is an important clinical challenge in the management of breast cancer." (PMID 28781955, 2017). "Conversely, treatment with Lapatinib, a small molecule EGFR/Erbb2 inhibitor used to treat breast cancer, has not been linked to cardiotoxicity." (PMID 28924210, 2017). "In summary, this study demonstrate that miR-1296-5p might be involved in the regulation of proliferation in human breast cancer cells via targeting ERBB2/mTORC1 signaling pathway." (PMID 29089858, 2017).
breast cancer (continued). "When they treated ErbB2 overexpressing breast cancer cells with the ErbB2 targeting monoclonal antibody trastuzumab, the cell viability could be significantly reduced in the 3D cultures, whereas the 2D monolayers were only marginally affected." (PMID 28417948, 2017). "PUVA also reduced p85(ErbB2) phosphorylation to induce apoptosis of ErbB2+ breast cancer models." (PMID 28349059, 2017). "Previously, it was shown that the paired box 2 gene product (PAX2), a transcription factor that physically associates with an ER binding site within the intron of the ERBB2 gene and inhibits the transcription of ERBB2, enhanced the sensitivity of breast cancer cells to tamoxifen treatment." (PMID 29299178, 2017). "Indeed, high Blimp1 expression levels are detected in invasive p130Cas/ErbB2 cells and correlate with metastatic status in human breast cancer patients." (PMID 28442738, 2017). "This study could be significant in targeting not only ERBB2 positive breast cancer due to CAR-T specificity for ERBB2, but also a myriad of other cancers that express the ERBB2 antigen." (PMID 28885562, 2017). "We reviewed the functional properties of the driver nodes found to have the highest impact in controlling the essential proteins; they are ERBB2, SRC, PDPK1, PRKDC, mTOR for breast cancer, ERBB2, AKT1, GSK3B, ABL1 in pancreatic cancer, and RET in ovarian cancer." (PMID 28871116, 2017). "Breast cancers are divided into different subtypes depending on the expression of hormone receptors, including estrogen receptor (ER), progesterone receptor (PR), and epidermal growth factor receptor 2 (HER2 or erbB2)." (PMID 29145850, 2017). "In particular, CIP2A overexpression has been reported in approximately 60% of ErbB2+ breast cancer samples and may have potential as a clinical predictor for lapatinib responsiveness." (PMID 28938602, 2017). "Lapatinib is approved by the FDA for the treatment of ERBB2 positive breast cancer patients." (PMID 28060735, 2017). "It has been demonstrated that lapatinib prevents mammary tumor development in mouse mammary tumor virus (MMTV)-erbB-2 transgenic mice; however, the chemopreventive effect in the study was based on long-term, high dose exposure to lapatinib (12 months, 75 mg/kg twice daily)." (PMID 28061785, 2017). "Our current study demonstrated that in ERBB2-positive breast cancer, ERRF also plays an important role, as ERRF sensitized such cells to lapatinib treatment, and higher levels of ERRF expression correlated with increased lapatinib sensitivity and better patient survival." (PMID 28415602, 2017). "ErbB2 overexpression defines a subtype of breast cancer (HER2+ subtype)." (PMID 28338617, 2017). "Triple negative breast cancer is characterized by the absence of the estrogenreceptor (ER), the progesterone receptor (PR) and low to normal levels of HER2,a receptor tyrosine kinase encoded by the ERBB2 gene that isoften amplified or overexpressed in breast cancer." (PMID 28521512, 2017). "Furthermore, knockout of HK2 suppressed tumor initiation and progression in KRAS-driven lung cancer and ErbB2-driven breast cancer mouse models." (PMID 29043013, 2017). "ERBB2 can activate mTORC1/p70S6K signaling in human breast cell lines and breast cancers." (PMID 29089858, 2017). "Notably, ERBB2 overexpression in breast cancer has become an independent diadynamic criterion of worse prognosis." (PMID 29163776, 2017). "In conclusion, our results showed, for the first time, that miR-1268b could reverse chemoresistance of breast cancer, at least partly, by targeting ERBB2 and suppressing PI3K/AKT pathway." (PMID 29163776, 2017). "We therefore analyzed these markers in phenformin-treated ErbB2-overexpressing breast cancer cells." (PMID 28947975, 2017).
breast cancer (continued). "Importantly, the ErbB2+ breast cancer subtype has been reported to be more responsive than the ErbB2-negative subtype to metformin and other biguanides." (PMID 28947975, 2017). "Autophagy protected ErbB2 overexpressing breast cancer cells from trastuzumab cytotoxicity." (PMID 28338617, 2017). "Collectively, H2-18 plus GDC-0941 could effectively inhibit tumor growth, suggesting the potential to be translated into clinic as an efficient strategy for ErbB2-overexpressing breast cancers." (PMID 28881779, 2017). "We extended our analysis to an ErbB2-expressing mouse breast cancer cell model." (PMID 28436416, 2017). "In breast cancer, overexpression of hyaluronan synthase 2 increases ErbB2-dependent signalling leading to disease progression, while suppression of hyaluronan synthase 2 leads to inhibition of tumorigenesis and progression of breast cancer." (PMID 27928742, 2017). "In breast cancer, trastuzumab has extended survival in patients with overexpression of ErbB2." (PMID 28338617, 2017). "Alternately, tumor-associated antigens (TSA) are usually expressed at low levels in normal tissues but are found to be overexpressed in cancer cells such the surface receptor, human epidermal growth factor 2 (HER2 or ERBB2) in breast cancer, and other malignancies." (PMID 29276510, 2017). "ERRF expression predicts the sensitivity to lapatinib in ERBB2 positive breast cancer." (PMID 28415602, 2017). "Herein, we aimed to establish CAR in CD3+ T-cells, isolated from human peripheral blood mononucleated cells that could subsequently target and induce apoptosis in the ERBB2 overexpressing human breast cancer cell line, SKBR3." (PMID 28885562, 2017). "MCL1 has been shown to upregulate ERBB2 expression in breast cancer cells." (PMID 28415602, 2017). "Our study also suggested that the combination of H2-18 with GDC-0941 may be a promising effective strategy for the treatment of ErbB2-overexpressing breast cancer." (PMID 28881779, 2017). "In this context, LPP enhances focal adhesion dynamics within ErbB2-expressing breast cancer cells." (PMID 28436416, 2017). "Although CNAs are an important event involved in tumorigenesis, their detection in clinical cancer genetics labs is generally limited to few cytogenetic-based assays focusing on gains of a single gene, such as ERBB2 used to determine breast cancer patient’s suitability for targeted therapy." (PMID 28928368, 2017). "Indeed, trastuzumab resistance is a common problem in ErbB2+ breast cancers because tumor cells can circumvent ErbB2 inhibition by activating IGF1R." (PMID 28947975, 2017). "We also tested whether ERRF expression correlates with prognosis in patients with ERBB2 positive breast cancer using the BreastMark Coexpression analysis tool." (PMID 28415602, 2017). "In breast cancer, it was reported that nearly 30% cases showed ERBB2 overexpression." (PMID 29163776, 2017). "It still remains unclear why Pten has such an interconnected role with isoform specificity in ErbB2-positve breast cancer." (PMID 28783168, 2017). "Hence, our results suggested that overexpression of miR-1268b confers chemosensitivity in breast cancer by suppressing ERBB2-mediated PI3K-AKT pathway and inducing apoptosis." (PMID 29163776, 2017). "Human epidermal growth factor receptor 2 [HER2] (also termed Her-2/neu and erbB-2) proteins are a type I family of epidermal growth factor receptors expressed on the cell surface; these proteins are over-expressed in approximately 30% of breast cancers." (PMID 28460461, 2017). "Moreover, it was declined in ERBB2-positive breast cancer samples compared with that in ERBB2-negative breast cancer tissues." (PMID 29089858, 2017).
breast cancer (continued). "In addition, inhibition of miR-21 synergistically increased the ability of chemotherapeutic agents and trastuzumab to reduce the viability of erb-b2 receptor tyrosine kinase (ERBB2; HER2)-positive breast cancer cells." (PMID 28474282, 2017). "Clinically, breast cancer is grouped into luminal A (LA), luminal B (LB), human epidermal growth factor receptor 2-positive (HER2+), and triple-negative (TN) subtypes according to estrogen receptor (ER), progesterone receptor (PR), and epidermal growth factor receptor ErbB2/HER2 (HER2) expression." (PMID 28938599, 2017). "Therefore, ERRF expression influences the apoptotic response of ERBB2 positive breast cancer cells to lapatinib." (PMID 28415602, 2017). "MiRNA-1268b / ERBB2 / PI3K signaling may become a potential target for reversing the chemoresistance of breast cancer." (PMID 29163776, 2017). "Similarly, several lines of evidence have indicated that HER2 (ERBB2) is an important positive regulator of the CSC population in HER2+ breast cancers and other tumors." (PMID 27845900, 2017). "We therefore decided to explore its involvement in p130Cas/ErbB2 mediated breast cancer invasion." (PMID 28442738, 2017). "We found that ErbB2 blocks anoikis of breast cancer cells by downregulationg a protein Perp that triggers apoptosis by an unknown mechanism." (PMID 29285258, 2017). "Thus, increased density of detached breast cancer cells strongly reduces Erk, phospho-Erk and ErbB2 levels in these cells and renders those cells that remain viable trastuzumab-resistant." (PMID 29285258, 2017). "Moreover, silencing of Blimp1 in N202-1A cells was sufficient to reduce cell invasion in vitro, further confirming that Blimp1 is critical for p130Cas/ErbB2-driven invasion in another cell model of breast cancer." (PMID 28442738, 2017). "It has been described that miR-23b is downmodulated in invasive acini, leading us to speculate that miR-23b may play a tumor suppressor role in the p130Cas/ErbB2 breast cancer model." (PMID 28442738, 2017). "In addition, the authors also demonstrated that Tid1 is capable of inhibiting avian erythroblastosis oncogene B 2 (ErbB-2) in mammary carcinomas by disrupting ERK1/2 and MAPK 1 signaling cascades leading to apoptosis." (PMID 28914774, 2017). "ERBB2 overexpression in human breast cancer leads to invasion and metastasis." (PMID 26899482, 2016). "On the other hand, breast cancer is a complex disease that is mainly grouped based on its hormone receptor subtype (estrogen receptor or progesterone receptor positivity) and amplification of the ERBB2 gene." (PMID 27754415, 2016). "In the present study, we investigated whether similar feedback control is employed for the ErbB2/ErbB3 heterodimer in breast cancer cells." (PMID 27531070, 2016). "Consequently, there is a need for new specific targets for the therapy of anti-ErbB2-resistant breast cancer, including Triple Negative Breast Cancer (TNBC), which lacks estrogen receptor (ER), progesterone receptor and ErbB2." (PMID 27894092, 2016). "Finally, interference with ERM functionality leads to receptor degradation and reduced cellular levels of ErbB2 and ErbB3 receptors in breast cancer cells." (PMID 27029001, 2016). "The high incidence of ErbB2 abnormal expression in this disease makes the involvement of nucleolin in ErbB2 signaling especially intriguing, and offers new insights on the development and progression of ErbB2-driven breast cancer, as well as on novel targets for cancer therapy." (PMID 27542246, 2016). "Notably, the GA analog 17-AAG combined with TZ showed increased clinical efficacy in ERBB2+ breast cancer patients that become resistant to TZ, highlighting HSP90 inhibitors as effective agents to overcome or prevent drug resistance." (PMID 27863425, 2016). "Our findings may facilitate the development of precision therapeutic regimens for erbB2-positive breast cancer patients who become resistant to erbB2-targeted therapy." (PMID 26621843, 2016).
breast cancer (continued). "Importantly, depletion of endogenous nucleolin in ErbB2-positive SKBR3 breast cancer cells resulted in a significant impairment of ErbB2 phosphorylation." (PMID 27542246, 2016). "These included Basal/Erbb2 Breast Cancer and Ovarian Cancer, Transcription/Translation and Mammary Stem Cell pathways that were induced, and Luminal Breast Cancer, Histone Methylation, Mitochondria and other metabolic as well as Cancer Associated pathways that were repressed." (PMID 26814435, 2016). "Likewise, IKK alpha activity is required for self-renewal of ErbB2/Her2-transformed mammary tumor-initiating cells and the canonical NF-κB pathway is active in normal luminal progenitor cells before transformation." (PMID 27708225, 2016). "ERBB2 amplification is a known oncologic driver in breast cancer, however, the role of ERBB2 mutation is not well defined." (PMID 27811364, 2016). "The observation that both low and high expression levels of ERBB2 – also a RTK involved in many epithelial cancers – are associated with the poor prognosis of primary breast cancers, illustrates that our finding does not stand completely on its own." (PMID 26909606, 2016). "Both ErbB2 overexpression and ErbB3 activation by HRG have been linked to breast cancer metastasis." (PMID 27351228, 2016). "Importantly, this enhanced tumorigenicity also occurs in human ErbB2-positive breast cancer patients; namely, nucleolin overexpression in these patients is associated with reduced patient survival rates and increased disease-risk." (PMID 27542246, 2016). "A future study on human breast cancer patients is necessary to determine whether there is indeed an interaction among alcohol drinking, ErbB2 status and the aggressiveness/progression of breast cancer." (PMID 27416801, 2016). "CCND1 and ErbB2 have been reported to play an early role in sporadic breast cancer." (PMID 27190992, 2016). "For instance, the UC San Diego Moores matched therapy cohort included 11 patients (13 %) with breast cancer who received endocrine therapy based on ER expression and 11 patients (13 %) with breast cancer who received HER2-directed therapy based on ERBB2 (HER2) amplification." (PMID 27782854, 2016). "We can speculate that p130Cas mirrors in ErbB2 positive breast cancer the function of Hsp90, protecting ErbB2 from degradation but at the same time, assembling a signaling platform that sustains and reinforces breast cancer growth, migration and invasion." (PMID 26716506, 2016). "While trastuzumab has been well established as successful against ERBB2-positive breast cancer, preclinical studies of the efficacy of trastuzumab against gastric cancer (GC) were largely restricted to a single cell line, NCI-N87, expressing extremely high levels of ERBB2." (PMID 26955870, 2016). "The high levels of APOBEC3 activity in the HER2+ subtype indicates that an increased gene dosage of ERBB2 may drive APOBEC3 in breast cancer, corroborating earlier observations by Roberts and colleagues." (PMID 27634334, 2016). "Two ErbB2-overexpressing breast cancer cell lines, BT-474 and SK-BR-3, were used in this study." (PMID 26999718, 2016). "Breast cancer cells over-expressing ErbB2 are more sensitive to alcohol-promoted aggressiveness." (PMID 27416801, 2016). "To assess the cytotoxic activity of biparatopic DARPins in vitro, we treated a panel of ErbB2-overexpressing breast cancer cell lines (BT474, HCC1419, HCC2218, SKBR3, AU565 and ZR75-30) with wild-type PI3K activity and a range of EGFR, ErbB3 and PTEN expression levels." (PMID 27255951, 2016). "Since ErbB2 remained continuously expressed in a panel of breast cancer cell lines treated with either agent, and no substantial increase in internalization nor degradation of ErbB2 was observed, we inspected the phosphostatus of ErbB2 as well as of ErbB3." (PMID 27255951, 2016). "The topoisomerase II alpha (TOP2A) and ERBB2 genes are located close to each other on the long arm of chromosome 17 and may be co-amplified in breast cancer." (PMID 27576528, 2016).